RNY1P13 (RNY1 pseudogene 13)
Gene: Miscellaneous RNA gene on chromosome 1 (114,727,720 to 114,727,824, forward strand). Ensembl gene ENSG00000201900.
Homologues: Orthologues: chimpanzee Y_RNA (98% identical), macaque Y_RNA (89% identical). Paralogues in human: RNY1 (90% identical), Y_RNA (90% identical), Y_RNA (89% identical), Y_RNA (88% identical), RNY1P11 (87% identical), Y_RNA (87% identical), Y_RNA (86% identical), Y_RNA (85% identical), Y_RNA (84% identical), RNY1P10 (83% identical), RNY1P8 (83% identical), Y_RNA (83% identical), and 99 more.